RN7SKP174 (RN7SK pseudogene 174)
Gene: Miscellaneous RNA gene on chromosome 7 (144,849,755 to 144,850,084, reverse strand). Ensembl gene ENSG00000200673.
Homologues: Orthologues: chimpanzee 7SK (99% identical). Paralogues in human: 7SK (88% identical), RN7SKP48 (82% identical), RN7SKP187 (82% identical), RN7SKP118 (81% identical), RN7SKP292 (81% identical), RN7SKP62 (81% identical), RN7SKP227 (80% identical), RN7SKP185 (79% identical), RN7SKP55 (78% identical), RN7SKP178 (76% identical), RN7SKP76 (75% identical), RN7SKP104 (74% identical), and 284 more.